IDO1 (indoleamine 2,3-dioxygenase 1)
Diseases named in the same sentence as IDO1 in open-access papers (continued):
Sharing a sentence is not in itself a finding about the gene and the disease.
cervical tumor (11 papers, 2015 to 2025). "In the margins of cervical tumors, where the tumors are surrounded by immune cells, tumor cells express IDO1; this is regarded as a consequence of T cell infiltration and local IFN-γ induction." (PMID 38540186, 2024). "Blockade of IDO1 contributes to shrinkage of CC (Blocking IDO1 Helps Shrink Bladder, Cervical Tumors, 2018)." (PMID 36685937, 2022). "It has been shown that IDO1 is highly expressed in cervical tumor cells." (PMID 33390854, 2021). "Similarly, IDO1 expression was also notably increased in cervical tumors than in normal cervix tissues." (PMID 33390854, 2021). "Also, we compared the relationships between IDO1 and IFNG gene expression and linked this to survival outcome using RNAseq data from cervical tumor samples published by The Cancer Genome Atlas (TCGA)." (PMID 30050535, 2018). "Indeed, TCGA analysis of 144 cervical tumor samples revealed a strong and positive correlation between IDO1 and IFNG mRNA expression levels (P < 0.001) and a significant association with improved DFS for high IDO1 and IFNG transcript levels (P = 0.031)." (PMID 30050535, 2018). "Moreover, the protein expression of IDO1 was also found to be higher in cervical tumor samples compared to other cancers." (PMID 28670312, 2017). "Our study aimed to investigate the influence of inhibiting IDO-1 and CXCR-2 on cervical tumor growth." (PMID 37626777, 2023). "Our results revealed that combined inhibition of IDO-1 and CXCR-2 significantly reduces the areas of cervical tumors (from 196.0 mm2 to 58.24 mm2 in R1 and 149.6 mm2 to 52.65 mm2 in R2), accompanied by regions of moderate dysplasia, decreased papillae, and reduced inflammation." (PMID 37626777, 2023). "Considering that the combined inhibition of IDO-1 and CXCR-2 (K14E7E2 + CT) exhibited a more significant effect in reducing cervical tumor areas compared to single-drug treatment in mice that developed CIN-III/CC (K14E7E2), we decided to utilize this regimen for our subsequent experiments." (PMID 37626777, 2023). "In addition, we compared the relationships between IDO1 and IFNG gene expression and clinical parameters using RNAseq data from 144 cervical tumor samples published by The Cancer Genome Atlas (TCGA)." (PMID 30050535, 2018).
fungal infections (11 papers, 2012 to 2023). "IDO-1 promotes fungal clearance and inhibits T-cell immunity and inflammation, exhibiting its importance in host susceptibility to fungal infections." (PMID 36776848, 2023). "To the best of our knowledge, we present the first study evaluating the role of TLR4 signaling and IDO-1 production by MDSCs in fungal infection, notwithstanding intriguing outcomes documented in other cell populations." (PMID 37524886, 2023). "In fungal infections, the importance of the IDO-1/Kyn/AhR axis in the generation of Treg cells and tolerogenic activities of DCs was demonstrated." (PMID 32647342, 2020). "It has been demonstrated in fungal infections the fundamental role of IDO1 in promoting the balance between T cell subpopulations." (PMID 28791025, 2017). "Indeed, in fungal infections, IDO1 modulates the mechanisms of host resistance and disease tolerance by inducing Treg cells and inhibiting Th17 differentiation." (PMID 28791025, 2017).
Granuloma (11 papers, 2020 to 2025). A compact, organized collection of mature mononuclear phagocytes, which may be but is not necessarily accompanied by accessory features such as necrosis. "IDO1-expressing myeloid cells appeared specific to TB granulomas, whereas PD-L1-expressing myeloid cells and a scarcity of activated T cells were also found in sarcoidosis-associated granulomas." (PMID 40588584, 2025). "TB granulomas appear to follow a consistent structural outline of spatially coordinated PD-L1 and IDO1 and myeloid core-infiltrating Treg cells and a striking absence of T cell activation." (PMID 35058616, 2022). "We find that IDO1 seems to be specific to TB granulomas, whereas PD-L1 and sparsity of activated T cells are also found in another granulomatous condition, sarcoidosis." (PMID 35058616, 2022). "It has previously been shown that IDO-1 expression was particularly high in the macrophage-rich inner layer of TB granulomas that correlated with higher Mtb burden." (PMID 36591229, 2022). "As in granulomas, immunoregulatory genes such as PD-L1, IDO1 and CD163 were upregulated in blood." (PMID 35058616, 2022). "Interestingly, iNOS- and Arg-1–producing cells were mostly localized at the periphery of the TB granulomas in cells with a mononuclear morphology, whereas IDO-1 expression was detected primarily inside the granulomas." (PMID 35092727, 2022). "The absence of IDO1+ myeloid cells in sarcoidosis granulomas is their clearest difference from TB granulomas." (PMID 38165044, 2024). "Although we detected high expression of IDO-1 in macrophages in the center of granulomas from TB as well as TB/HIV co-infected tissues, arginase-1 expression was mostly confined to the T cell rich areas localized at the periphery of the TB granulomas, surrounding the cores of the lesions." (PMID 36591229, 2022). "Macrophages co-expressing the M2-marker CD163 together with IDO-1 localized within the suppressive rim of necrotic lung granulomas in non-human primates and humans and may prevent Mtb-specific T cells from reaching infected cells within the necrotic centers, which would promote Mtb persistence." (PMID 36591229, 2022). "Indoleamine 2,3-dioxygenase 1 (IDO1), the enzyme which catalyzes the catabolism of tryptophan, has been found to be significantly increased in the Mtb granuloma in non-human primate models and has been shown to be an effective biomarker for active tuberculosis infection." (PMID 32984072, 2020).
renal carcinoma (11 papers, 2011 to 2026). A carcinoma arising from the epithelium of the renal parenchyma or the renal pelvis. "In a previous study, we showed that activation of the kynurenine (KYN) pathway promoted renal cancer cells’ survival, migration, and chemoresistance and that increased accumulation of KYN in ccRCC was sustained by IDO1+ macrophages." (PMID 36902242, 2023).
diffuse large B-cell lymphoma (10 papers, 2018 to 2024). "In other lymphomas such as diffuse large B cell lymphoma (DLBCL), IDO1 expression and Kyn levels have been correlated with a poor prognosis." (PMID 33920868, 2021). "In addition, CYP1B1 expression was positively correlated with both IDO1 and TDO2 expression in skin melanoma (SKCM), squamous lung carcinoma (LUSC), diffuse large B-cell lymphoma (DLBC) and pancreatic adenocarcinoma (PDAC)." (PMID 32782249, 2020). "A recent report showed that AhR and its activating enzymes, IDO1 and tryptophan 2,3- dioxygenase (TDO), were highly expressed in diffuse large B-cell lymphoma (DLBCL) patient samples and were inversely correlated with patient survival." (PMID 38807762, 2024).
esophageal squamous cell carcinoma (10 papers, 2018 to 2025). Esophageal squamous cell carcinoma (ESCC) is a type of esophageal carcinoma (EC) that can affect any part of the esophagus, but is usually located in the upper or middle third. "A study on esophageal squamous cell cancer revealed similar results with respect to IDO1 enhanced after neoadjuvant therapy and associated with poor pathological response and prognosis." (PMID 40062505, 2025). "High IDO1 mRNA levels were associated with worse overall survival (OS) in both esophageal squamous cell carcinoma (SCC) (P = 0.02) and adenocarcinoma (AC) (P = 0.036)." (PMID 29805749, 2018). "IDO1 expression is upregulated in response to (radio)chemotherapy in patients with esophageal squamous cell cancer and predicts poor response and prognosis." (PMID 40062505, 2025). "IDO1 is one of the most important immunosuppressive proteins in esophageal squamous cell carcinoma (ESCC)." (PMID 33828565, 2021). "High IDO1 mRNA levels were significantly correlated with decreased patient survival for both esophageal SCC and AC." (PMID 29805749, 2018). "Using mRNA expression data from TCGA for esophageal SCC and AC, expression of IDO1, PD-1, PD-L1, CTLA-4, Her2, and OX-40 was evaluated." (PMID 29805749, 2018). "Growing evidence highlights the vital role of tryptophan (Trp) metabolism in esophageal squamous cell carcinoma (ESCC), particularly involving key enzymes such as IDO1 and TDO2." (PMID 40821701, 2025). "This study investigated the expression pattern of IDO1 in TME and its impact on prognosis and therapeutic response of patients with esophageal squamous cell carcinoma (ESCC)." (PMID 39351094, 2024). "In this study, we investigated the changes of tumor IDO1 expression and CD8+ tumor-infiltrating lymphocytes (TILs) status in tumor microenvironment (TME) after neoadjuvant chemoradiotherapy (NCRT) or neoadjuvant chemotherapy (NCT) in esophageal squamous cell carcinoma (ESCC), respectively." (PMID 32733806, 2020).
Insulin resistance (10 papers, 2018 to 2025). Increased resistance towards insulin, that is, diminished effectiveness of insulin in reducing blood glucose levels. "The gut microbiome shifted in pregnant mice accompanied by IDO1-dependent kynurenine production, intestinal inflammation, and pregnancy-associated insulin resistance, which were reversed in IDO1-knockout." (PMID 39462700, 2024). "Pharmacologic and genetic inhibition of IDO1 lowered the levels of KYN and reversed pregnancy-associated insulin resistance." (PMID 36766803, 2023). "As compared to PBS-treated Ido1−/− mice, Kyn significantly enhanced body weight gain and aggravated insulin resistance in Ido1−/− mice during the course of HFD induction." (PMID 35715443, 2022). "Likewise, pharmacological inhibition of IDO1 activity with L-1methyl tryptophan (1MT) ameliorates insulin resistance upon HFD-feeding or in genetically obese ob/ob mice." (PMID 36144238, 2022). "In the Trp-Kyn pathway, the rate-limiting enzyme, indoleamine 2,3-dioxygenase 1 (IDO1), diminishes insulin resistance by reducing inflammation, suggesting that tryptophan metabolism reduces the complications of T2DM." (PMID 39456421, 2024). "Indeed, genetic ablation of Ido1 protects mice from HFD-induced adiposity, insulin resistance, steatohepatitis, and macrophage infiltration of liver and adipose tissue." (PMID 36144238, 2022). "Therefore, we next investigated whether brain metabolites of HFD mice treated with GaELNs could modulate IDO1-AHR pathway and reverse the insulin resistance in the HFD fed mice." (PMID 35154484, 2022).
ischemia (10 papers, 2014 to 2022). A hypoperfusion of the BLOOD through an organ or tissue caused by a PATHOLOGIC CONSTRICTION or obstruction of its BLOOD VESSELS, or an absence of BLOOD CIRCULATION. "IDO1 expression was upregulated in macrophage cells of coronary artery thrombus tissues indicating that IDO1 was involved in the ischemia injury and impaired wound healing." (PMID 36405744, 2022). "Currently, there are no data on how the induction of IDO1 in NK cells translates into the course of ischemia-induced AKI." (PMID 35682852, 2022). "Thus, it is possible that IDO1 could play a dual function in the inflammatory response during IRI, depending on the timing of ischemia and the environmental conditions." (PMID 35682852, 2022).
myeloma (10 papers, 2012 to 2023). "The suppression of IDO1 induction by carfilzomib could enhance its therapeutic activity in myeloma, a problem potentially exacerbated by the apparent ability of carfilzomib alone to induce some IL1B and IL6 expression." (PMID 35371018, 2022). "In addition, the proteasomal S20 serine protease inhibitor carfilzomib, used in the treatment of myeloma, prevented the induction of IDO1 and cytokine gene expression, potentially contributing to its clinical anti-cancer activity." (PMID 35371018, 2022). "In this respect, both TGF-β and IL-10 are known to modulate IDO1 and may be expressed by the myeloma cells during progressive disease." (PMID 23232072, 2012). "Although our results showed an upregulation of genes associated to cytotoxicity in the BM of patients with SMM compared to MGUS, we also found overexpression of inhibitory molecules such as LAG-3, TIGIT and IDO1, which may affect the anti-myeloma immune response in SMM." (PMID 34880879, 2021). "However, we also found overexpression of inhibitory molecules such as LAG-3, TIGIT and IDO1, which may affect the anti-myeloma immune response in SMM." (PMID 34880879, 2021). "The percentage of NY-ESO-1-specific CD8+ T cells was significantly lower in KYNhi MM patients and was negatively correlated with Treg-cell expansion, implying that IDO1 activity may affect the anti-myeloma immune response either directly or indirectly, through the Treg compartment." (PMID 23232072, 2012). "Our interest in HGF as a candidate stimulus driving IDO1 expression in MM stems from studies underpinning the role of HGF in myeloma pathogenesis and from our previous report on the ability of HGF to induce IDO1 in human DC." (PMID 23232072, 2012).
nasopharyngeal carcinoma (10 papers, 2019 to 2025). A carcinoma arising from the nasopharyngeal epithelium. "While BTZ downregulates IFN-γ-induced IDO expression in nasopharyngeal carcinoma cells, it restores IDO1 protein levels in DCs from non-obese diabetic mice by inhibiting proteasomal degradation." (PMID 39120289, 2024).
psoriasis (10 papers, 2014 to 2025). An autoimmune condition characterized by red, well-delineated plaques with silvery scales that are usually on the extensor surfaces and scalp. "Indoleamine 2,3-dioxygenase 1 (IDO1) is an enzyme known to suppress immune responses, and several reports have showed that it is associated with psoriasis." (PMID 32752186, 2020). "Although B cells play important roles in the pathogenesis of both MS and psoriasis, the potential role IDO1/2 plays in mediating B cell function in these models remains to be determined." (PMID 35493480, 2022). "While in cancer, IDO1 is preferentially upregulated, in chronic inflammatory diseases such as psoriasis and atopic dermatitis, elevation of KYNU was found to be more pronounced than that of IDO1." (PMID 32384670, 2020). "In patients with psoriasis, immune cells including dendritic cells and CD4+ T lymphocytes have a defect in upregulating IDO1 in response to inflammation associated with the severity of the disease." (PMID 32752186, 2020). "Although IDO1 has a protective effect in psoriasis by inducing regulatory T cells, immune cells from patients with psoriasis have a defect in upregulating IDO1 in response to inflammation which is proportional to the disease severity." (PMID 32752186, 2020). "Moreover, serum IDO1 activity was confirmed to be increased in psoriasis, where immune cells from patients with psoriasis are defective in inducing IDO1 upregulation in response to inflammatory stimuli." (PMID 35778590, 2022). "The relationship between the pathophysiology of psoriasis and IDO1 has previously been reported." (PMID 32752186, 2020). "Other B cell-mediated autoimmune and inflammatory diseases are also affected by IDO1 and IDO2, including multiple sclerosis (MS) and psoriasis." (PMID 35493480, 2022). "Previous work has identified KYNU as one of the most upregulated genes in lesional skin of patients with psoriasis and atopic dermatitis, and preferential upregulation of KYNU over IDO1 and TDO corelated with disease severity in these settings." (PMID 32970636, 2020). "While KYNU is one of the top upregulated genes in both atopic dermatitis and psoriasis, induction of KYNU was lower than that of IDO1/TDO in HS skin." (PMID 32970636, 2020). "Our results also show that, in the epidermis of patients with psoriasis and WT mice treated with IMQ, IDO2 was expressed but IDO1 was not." (PMID 32752186, 2020).
schizophrenia (10 papers, 2016 to 2024). A major psychotic disorder characterized by abnormalities in the perception or expression of reality. "This interleukin-1β has been shown to enhance the synthesis of IDO1, facilitating the conversion of tryptophan to kynurenine—a pathway that has been altered in patients with schizophrenia." (PMID 39458380, 2024). "Measurements of these additional determinants has been suggested to be able to contribute to a better understanding of the TRP status and IDO1 activity in IDO1 involved cancer and other diseases such as schizophrenia." (PMID 33557876, 2021). "Here we examined the relative expression of DRD1, DRD2 and IDO1 and IDO2 genes transcription in MK-801 model schizophrenia group and T. gondii infected rat brain and subsequent neurotransmitter changes." (PMID 36950587, 2023).
cutaneous melanoma (9 papers, 2020 to 2024). A primary melanoma arising from atypical melanocytes in the skin. "However, skin melanoma was an exception to this, where high expression of IDO-1 was associated with better prognosis." (PMID 34367262, 2021). "Furthermore, IDO1 expression has been correlated with the Breslow thickness of the primary cutaneous melanoma." (PMID 38791968, 2024). "Nevertheless, the frequency of the somatic mutations that we detected both in IDO1 and HLA-DRA, suggests that these are common events taking place in skin melanoma and could be involved in hindering patient response to ICI therapies." (PMID 36389735, 2022). "IDO1 and LAG3 overexpression, which was evident in CYT-high skin melanomas, provides an alternative immunosuppressive barrier that is needed to hamper the antitumor activity of CTL and NK cells, in these tumors." (PMID 33779796, 2021). "Our data reveal that IDO1 and HLA-DRA are frequently mutated in skin melanoma, but these mutations do not seem to associate with their gene expression." (PMID 36389735, 2022).
mood disorder (9 papers, 2014 to 2026). A cognitive disorder a disturbance in which the person's mood is hypothesized to be the main underlying feature. "The stimulation of IDO-1 by the inflammatory cytokines in mood disorders leads to the activation of the tryptophan/kynurenine pathway, triggering the formation of the kynurenic and quinolinic acids, among other metabolites." (PMID 34040126, 2021). "Several studies have provided evidence that overactivation of IDO-1 and subsequent TRYP depletion may be associated with depression and other mood disorders." (PMID 35656104, 2022).
pancreatic ductal adenocarcinoma (9 papers, 2021 to 2025). An infiltrating adenocarcinoma that arises from the epithelial cells of the pancreas. "The induction of indoleamine 2,3-dioxygenase 1 (IDO1), a tryptophan degrading enzyme, in pancreatic ductal adenocarcinoma leads to increased formate overflow, which was shown to be utilized by surrounding pancreatic stellate cells for purine synthesis." (PMID 38698089, 2024). "Neoplastic cells of non-immunogenic pancreatic ductal adenocarcinoma (PDAC) express indoleamine 2,3-dioxygenase 1 (IDO-1), an immunosuppressive enzyme." (PMID 36517670, 2023). "Although the expression of IDO was not evaluated here, upregulation of both IDO1 and IDO2 have been shown in human pancreatic ductal adenocarcinoma and a more detailed evaluation of IDO involvement in AP is the focus of a separate, on-going study." (PMID 33925729, 2021).